HIF1A (hypoxia inducible factor 1 subunit alpha)
Diseases named in the same sentence as HIF1A in open-access papers (continued):
Sharing a sentence is not in itself a finding about the gene and the disease.
tumor (continued). "Moreover, HIF-1α rs11549465 C>T is linked to increased tumor microvessel density which makes contribution to the cancer progression." (PMID 31762805, 2019). "Furthermore, high tumor levels of HIF-1α have been associated with apoptosis and higher survival rates." (PMID 31470659, 2019). "HIF1A is an adaptive factor that is highly expressed in the hypoxic environment, which is closely related to the expression of various tumor-associated factors." (PMID 31930127, 2019). "Thus, the loss of tumor-suppressor function of von Hippel Lindau tumor-suppressor protein (pVHL) by stabilizing HIF-1α up-regulates the expression of a number of hypoxia-responsive factors including VEGF-A." (PMID 31540455, 2019). "HIF-1α expression is linked to: angiogenesis, tumor metastasis, and poor cancer outcomes." (PMID 31366108, 2019). "Indeed, SIRT1, SIRT3 and SIRT6 downregulation was associated with HIF-1α-mediated glycolytic metabolism activation, tumor growth and glucose homeostasis." (PMID 30986931, 2019). "Additionally, lactate-induced HIF-1α stabilization stimulates polarization of tumor-associated macrophages, contributing to immunosuppression." (PMID 30986931, 2019). "Besides, HIF-1α inhibit the immunosuppressive function of Tregs, which causes the function of Tregs mainly dependent on free fatty acids in tumor microenvironment." (PMID 31519198, 2019). "However, despite the loss of HIF-1α and maintenance of a low-proliferative phenotype, CI-deficient tumor growth persists." (PMID 30796225, 2019). "The tumor suppressor VHL encodes a ubiquitin ligase enzyme that presides to constant HIF1α degradation in the presence of molecular oxygen, when the transcription factor is hydroxylated by prolylhydroxylase domain-containing (PHD) enzymes for VHL recognition and proteasome degradation." (PMID 30728892, 2019). "Bioinformatics analysis of whole transcriptome profiling followed by quantitative protein and targeted gene expression validation experiments reveals that IKKα loss can result in the up-regulation of activated HIF-1-α protein to enhance NSCLC tumor growth under hypoxic conditions in vivo." (PMID 31792060, 2019). "Clinicopathologic analysis revealed that the strongly expressed HIF‐1α in the cancer group was associated with the depth of tumor invasion, pathologic stage of cancer, advanced stage according to the American Joint Committee on Cancer classification, and shorter overall survival time." (PMID 31411003, 2019). "HIF-1α G1790A has been associated with enhanced tumor-produced HIF-1α and cancer progression." (PMID 31419966, 2019). "Under hypoxic conditions, high HIF-1α expression leads to loss of T cell anti-tumor function." (PMID 31519198, 2019). "Furthermore, a noticeable frequency of genetic alterations in tumor cells is associated with the enhanced expression of HIF-1α." (PMID 30754624, 2019). "Loss of HIF-1α is associated with decreased tumor growth, vascularization, and energy metabolism." (PMID 31350968, 2019). "IKKα loss can up-regulate HIF-1α, enhancing tumor growth under hypoxia." (PMID 31792060, 2019). "In this study, we aimed to reveal the mechanisms underlying the tumor-promoting effects of 3MC in RECs, with a particular focus on HIF1α/HDAC1 and RhoA, and to determine whether simvastatin can prevent these effects." (PMID 30872677, 2019). "HIF-1α was associated with a higher rate of lymph node metastasis and advanced tumor stage." (PMID 30662458, 2018). "Indeed, overexpression of HIF-1α has been confirmed in many primary tumor biopsies, and is associated with resistance to therapy, and poor outcomes." (PMID 30560881, 2018). "HIF-1α target genes encoding for proteins that will enhance neovascularization, increase anaerobic glycolysis, decrease mitochondrial functions, and oxidative phosphorylation to allow the tumor cells to adapt to the hostile tumor microenvironment." (PMID 29628507, 2018).
tumor (continued). "The great variation in HIF-1α expression and different reaction patterns to hypoxia observed in our study could be explained by the pronounced tumor heterogeneity, which might be associated to different resistance mechanisms in tumors." (PMID 29708435, 2018). "However, IDH mutant tumor cells downregulate expression of hypoxia-associated genes, such as HIF1α, and increases the risk of reactive oxygen species-mediated DNA damage." (PMID 30333031, 2018). "Indeed, deficiency in HIF-1α results in decreased suppressive activity and increased anti-tumor response." (PMID 30194424, 2018). "Also, there was a positive association between high P4HA2 expression either within tumour epithelial cells or stromal cells and high HIF-1a expression." (PMID 30410060, 2018). "This tumor glycolysis, associated to more aggressive tumor phenotype, is directly controlled by major signal transduction pathways involved in oncogenesis often associated with HIF-1α activity." (PMID 30045750, 2018). "However, the role of hypoxia and the associated increase in HIF-1α protein levels on tumor invasiveness remained unclear." (PMID 30560881, 2018). "According to the study of a large number of malignant primary tumor tissues from pheochromocytomas and paragangliomas, PD-L2 expression but not PD-L1 expression is significantly associated with stronger hypoxia-driven HIF-1α and carbonic anhydrase 9 (CAIX)." (PMID 30061885, 2018). "Thus, overexpression of HIF-1α is associated with tumor aggressiveness and prognosis in several malignancies, including UCB." (PMID 29135410, 2018). "Colegio and colleagues further demonstrated that HIF-1α expression in tumor macrophages induce M2-associated genes such as VEGF, arginase 1 (Arg1), macrophage galactose-type lectin-1 (Mgl1) and macrophage galactose-type lectin-2 (Mgl2) in a colon carcinoma mouse model." (PMID 30619850, 2018). "In addition, overexpression of the transcription factors Hypoxia-Inducible Factors HIF-1α and -2α was linked to tumor progression of kidney tumorigenesis." (PMID 30250638, 2018). "We next considered the possibility that loss of HIF2α may increase HIF1α protein levels, leading to the promotion of tumor growth." (PMID 29993038, 2018). "HIF-1α plays a critical role in driving the characteristic changes in cell morphology causing a mesenchymal-like phenotype and facilitating the metastasis of tumor cells." (PMID 29592811, 2018). "PD-L1 is a novel transcription target of HIF2α and HIF1α in tumor cell deficient in VHL." (PMID 29535842, 2018). "However, HIF1α expression is lost in 30–40% of overt ccRCCs, since HIF1α acts as a tumor suppressor during further progression of ccRCC by attenuating autonomous VHL-deficient tumor cell proliferation." (PMID 29938199, 2018). "Moreover, WWOX deficiency in hepatocytes combined with diethylnitrosamine treatment increased the tumor burden, which was associated with increased HIF1α levels and target gene transactivation." (PMID 29724996, 2018). "Robust tumor growth results in hypoxia, which promotes the stabilization of the oxygen-sensitive transcription factor hypoxia-inducible factor-1alpha (HIF-1α) that induces the expression of multiple genes implicated in angiogenesis, metabolism, and cell survival." (PMID 28052029, 2017). "Seven studies had reported on the association of HIF-1α expression with tumor histology." (PMID 28521842, 2017). "Secondly, our results, that stem cell-mediated invasion depends on aberrant induction of drugable targets, such as mTOR, HIF-1α or MMPs, might open a new window of opportunity to minimise the therapy-associated tumour risk." (PMID 28928383, 2017). "RFA also increased HIF-1α expression in the rim of viable cells immediately adjacent to the ablation zone, which is possibly related to reversible cell injury or regional reduction in tumor perfusion caused by vascular thrombosis." (PMID 28978941, 2017).
tumor (continued). "Furthermore, the hypoxic signal mediated by the HIF-1α-ARNT transcriptional complex also causes expression of genes associated with tumour growth and metastasis." (PMID 28798482, 2017). "c-Myc and HIF1a are transcription factors that are implicated in tumor proliferation and survival." (PMID 29048387, 2017). "Inflammation in tumor is associated with a close collaboration between HIF-1α and NF-κB." (PMID 29099748, 2017). "Firstly, we found that endogenous STK33 interacted with hypoxia-stabilized HIF-1α; secondly, deletion of STK33 in tumor cells subjected to low oxygen atmosphere resulted in a reduced HIF-1α accumulation which thirdly, was associated with impaired hypoxia-induced HIF-1α promoter activity." (PMID 29100402, 2017). "We hypothesized that the differential sensitivity of intratumoral Hif1-α to exercise would be linked to alterations in tumor metabolism." (PMID 29254140, 2017). "Therefore, any aberrant stimulation of this pathway, which in cancer often occurs through growth factors, hormones, or oncogenes/tumor suppressor mutations, leads to the activation of HIF-1α, even in normoxic conditions." (PMID 29230384, 2017). "Thus, HIF-1α likely also contributes to EBV-associated tumorigenesis given a small amount of lytic infection is known to enhance tumor growth." (PMID 28617871, 2017). "Tumor progression, limited efficacy of current standard treatments, and the rise in patient mortality are associated with gene expression caused by the synergistic action of intratumoral hypoxia and HIF-1α activation." (PMID 29097800, 2017). "Interestingly, flow-sorted, tumour-associated NK cells from MC38 tumour-bearing HIF-1α KO mice showed similar expression of sVEGFR1 at the mRNA and protein level across genotypes." (PMID 29150606, 2017). "In addition, ID proteins are implicated in tumor angiogenesis and induce expression of pro-angiogenic factors including hypoxia-inducible factor-1α (HIF1α), vascular endothelial growth factor A (VEGFA), interleukin-6 (IL-6)." (PMID 28881649, 2017). "At the same time, HIF1α is associated with immune escape involving other mechanisms such as shedding of cell surface immune checkpoint regulators like MIC1 thus causing resistance of tumor cells to NK cell attack." (PMID 28447025, 2017). "However, tumor hypoxia induced by arterial embolization causes vigorous angiogenesis following up-regulation of the hypoxia-inducible factor (HIF)-1α pathway; this consequently influences tumor recurrence and the survival of patients." (PMID 28373713, 2017). "VHL mutations are associated with a strong HIF-1α-dependent miR-210 over-expression and accumulation of HIF-1α in most tumor cells whereas SDHx mutations are associated with mild increase of miR-210 and the presence of a heterogeneous, HIF-1α-positive and HIF-1α-negative, tumor cell population." (PMID 28036268, 2017). "To test this hypothesis, we analysed the effect of NK cell HIF-1α deficiency in tumours that are less susceptible to NK cell-mediated lysis as confirmed by in vitro activation and in vitro cytotoxicity assays." (PMID 29150606, 2017).
tumor (continued). "Furthermore, loss of HIF-1α in CD8+ T cells reduced tumor infiltration and tumor cell killing, and altered tumor vascularization." (PMID 29136509, 2017). "HIF-1α also directly binds to a hypoxia response element in the promoter of the gene encoding immune checkpoint molecule PD-L1, and hypoxia thereby increases expression of PD-L1 on MDSCs, tumor cells, DCs, and macrophages." (PMID 28066431, 2016). "Furthermore, survivin depletion by siRNA in RasG12V-IκBα-derived tumors leads to smaller tumor formation characterized by lower mitotic index and reduced expression of the tumor-associated marker HIF1α, VEGF and CD51." (PMID 26771605, 2016). "Furthermore, imaging markers of increased tumor metabolism and low tumor blood flow are associated with overexpression of stromal HIF-1α and a hypoxia gene signature." (PMID 27634881, 2016). "First, the concentration of circulating succinate (and HIF1α activity) in patients with tumours harbouring mutations in SDH is higher than in the healthy population; second, succinate can signal through its receptor GPR91 on dendritic cells in order to modulate the immune response." (PMID 27083002, 2016). "HIF-1α and associations with clinico-pathologic tumor and molecular characteristics." (PMID 26760782, 2016). "Our findings indicate that loss of VHL could be driving tumour cell dissemination through stabilization of HIF-1α in RCC." (PMID 27358011, 2016). "Additionally, a strong association between HIF-1α expression and Ki-67 proliferative rate in tumor cells was seen in our study." (PMID 26760782, 2016). "We selected these genes because all six were present in the angiogenesis signature unique to PDAC, because CYP1B1 was the most significantly and highly up-regulated, and because ANGPT1, its receptors TIE1 and TEK, and HIF1A are commonly associated with pathways that enhance tumor angiogenesis." (PMID 26586478, 2016). "Through the way, HIF-1α could regulate target genes which are associated with crucial aspects of tumor biology including angiogenesis, energy metabolism and vasomotor function, and thus make the tumor cell adaptive to the intratumoral hypoxia." (PMID 27606158, 2016). "HIF-1α plays a crucial role in cancer progression by activating the transcription of a broad range of genes involved in the pathophysiology of cancer, including genes implicated in tumor growth, metastasis, angiogenesis, invasion, and metastasis." (PMID 27314329, 2016). "Whether HIF-1α activation is a cause or a consequence of lipid accumulation in metastatic tumor cells remains to be uncovered." (PMID 27588494, 2016). "Moreover β-arr1 knock-down hampers the release of tumor cells into the circulation and metastatic dissemination, underlying the pathobiological relevance of nuclear β-arr1/HIF-1α-transcriptional mechanism." (PMID 26909598, 2016). "When tumor increases its size, the diffusion of nutrient and oxygen in tumor mass is no longer efficient and new vessels are formed to supply this deficiency (e.g. tumor hypoxia, HIF-1α nuclear expression levels and de novo angiogenesis are recognized interconnected events in cancer)." (PMID 27145373, 2016). "However, high tumor volume estimated by MRI tended to be associated with high stromal HIF-1α expression (p = 0.21)." (PMID 27634881, 2016). "One possible mechanism by which hnRNP A18 could contribute to cellular migration and proliferation is through regulation of TRX and HIF-1α which both have been associated with these tumor promoting events." (PMID 26824423, 2016).
tumor (continued). "Furthermore, high stromal HIF-1α expression tended to be associated with higher tumor maximum and mean standardized uptake value (SUVmax, SUVmean) and metabolic tumor volume (MTV) (p ≤ 0.17 for all)." (PMID 27634881, 2016). "In addition, high expression of HIF-1α in the tumor stroma was significantly associated with reduced survival (p = 0.005) and tend to be more frequent in lesions with low epithelial HIF-1α expression (p = 0.24, data not shown)." (PMID 27634881, 2016). "HIF1α stabilization due to loss of VHL decreased tumor growth." (PMID 26841847, 2016). "In addition to roles in adaptation to hypoxia and tumor development, HIF-1α activation has recently been associated with innate immunity against infections." (PMID 27624128, 2016). "Moreover, HIF-1α expression in tumor-associated macrophages enhances the T cell suppressive capacity of these cells; HIF-1α also causes upregulation of PD-L1 on MDSC, exacerbating their suppressive capacity." (PMID 26046638, 2015). "Indeed, HGF is a well-recognized proangiogenic mediator which inhibition reduces tumor growth and metastasis, as well HIF-1α, which is associated with poor prognosis in cancer due stimulation of VEGFR+ cells migration to the tumor." (PMID 26099922, 2015). "Cultivation of tumour slices required organotypic support materials and atmospheric oxygen for maintenance of integrity and was associated with significant temporal and loco-regional changes in protein expression, for example HIF-1α." (PMID 26647838, 2015). "Also noted were marked decreases in tumor volume, vascularity and proliferative index, associated with the downregulation of HIF1α and ABCG2, and increased intracellular concentrations of active topotecan." (PMID 26623560, 2015). "Moreover, HIF-1α, previously implicated in cancer stem-cell chemo-resistance, is downregulated in chemo-residual TN tumor cells from our model." (PMID 26141457, 2015). "We next sought to determine whether HIF-1α was implicated in metformin-mediated inhibition of in vivo tumor angiogenesis." (PMID 26625311, 2015). "Additionally, mutation in the tumour suppressor gene PTEN led to hypoxia-independent HIF-1α accumulation and to activated HIF-1-mediated proangiogenic gene expression." (PMID 26146622, 2015). "Tumour hypoxia is associated with many features of tumour aggressiveness including increased cellular proliferation, inhibition of apoptosis, increased invasion and metastasis, and chemoresistance, mostly mediated through hypoxia-inducible factor (HIF)-1α." (PMID 26205780, 2015). "The hypoxia-induced synthesis of HIF-1α causes modification of tumor microenvironment." (PMID 24745019, 2014). "Increased expression of the transcription factor, HIF-1α, in tumor cells is a hallmark of hypoxia, and HIF-1α plays a central role promoting tumor cell survival and growth during hypoxic conditions by changing the expression profile of many genes particularly angiogenic factors such as VEGF." (PMID 25140303, 2014). "Besides being induced by environmental hypoxia or growth factors, HIF-1α expression and stabilization in MM cells can arise from genetic abnormalities such as loss of tumor suppressor activity." (PMID 24732040, 2014). "Current data underline how HIF1-α may trigger broader effects than those related to angiogenesis and support tumor growth also by promoting local immune suppression." (PMID 24605112, 2014). "This may offer a possible explanation for the observed strong statistical association of HIF-1α overexpression with advanced tumor invasion, lymph node spread, vascular invasion, and distant metastasis." (PMID 24647137, 2014). "The data of our study showed that high RBP2 expression is common in stage I NSCLC tissues and is significantly associated with tumor size, high HIF-1α expression, high VEGF expression and a poor prognosis, suggesting that the RBP2 protein is involved in the aggressive progression of NSCLC." (PMID 25162518, 2014).